PGAM5 (PGAM family member 5, mitochondrial serine/threonine protein phosphatase)
Diseases named in the same sentence as PGAM5 in open-access papers (continued):
Sharing a sentence is not in itself a finding about the gene and the disease.
myocardial ischemia (3 papers, 2022 to 2024). A disorder of cardiac function caused by insufficient blood flow to the muscle tissue of the heart. "In mice subjected to myocardial ischemia/reperfusion injury, suppression of Pgam5 interrupted Keap1-mediated Bcl-xL degradation and promoted cardiomyocyte survival." (PMID 37781037, 2023). "Early studies reported that PGAM5 is markedly elevated in response to cardiac stress resulting from myocardial ischemia–reperfusion injury, chronic doxorubicin exposure, and lipopolysaccharide exposure." (PMID 39285950, 2022). "This concept is further validated by our recent study, which showed that cardiac-specific Pgam5 knockout (Pgam5-KO; Pgam5CKO) mice are less vulnerable to myocardial ischemia–reperfusion injury due to improved MQS." (PMID 39285950, 2022).
viral infection (3 papers, 2020 to 2024). "Specifically, STIP1, PGAM5, and AKAP8 were over-expressed in VM samples and associated with viral infections." (PMID 38902725, 2024). "Collectively, our study highlights PGAM5 as an important regulator for IFNβ production mediated via the TBK1/IRF3 signaling pathway in response to viral infection." (PMID 32433485, 2020). "PGAM5 regulates the activity of inflammasome and caspase 1 in BMDMs and contributes to IFN-β production in response to viral infection by promoting the TBK1 (TANK-binding kinase 1)/IFN regulatory factor 3 (IRF3) signaling pathway." (PMID 37771598, 2023).
acute pancreatitis (2 papers, 2023 to 2026). An acute inflammatory process that leads to necrosis of the pancreatic parenchyma. "Our findings establish PGAM5 as a central node in ferroptosis regulation and implicate its pathogenic role in acute pancreatitis." (PMID 41723122, 2026). "Furthermore, pharmacological inhibition of PGAM5 attenuates arginine-induced acute pancreatitis, highlighting its therapeutic potential." (PMID 41723122, 2026).
breast carcinoma (2 papers, 2022 to 2024). "In other types of tumors or diseases, PGAM5 is used as a mediator of signaling pathways, such as the RIP1/RIP3/PGAM5 pathway in breast cancer, the PGAM5-CypD pathway in prolactinoma, and the Ripk3/Pgam5 signaling pathway in septic cardiomyopathy, to induce necroptosis." (PMID 36523972, 2022). "In human breast cancer, it has been shown that necrosis can occur through finely tuned regulation of a series of pro-necrotic genes including MLKL, RIPK1, RIPK3, PGAM5, and DFNA520." (PMID 38773214, 2024).
cognitive deficits (2 papers, 2025 to 2026). "Subsequent MWM testing assessed whether therapeutic strategies against Pgam5 alleviate cognitive deficits resulting from ICH." (PMID 41201111, 2026). "As expected, both PARL overexpression and PGAM5 knockdown could rescue the Meth‐induced cognitive impairments." (PMID 40013375, 2025).
diabetes (2 papers, 2022). "In summary, the present work suggests that diabetes-induced PGAM5 overexpression contributes to DCM through PHB2 dephosphorylation, disrupting the stabilizing effect of PHB2 on MQS in cardiomyocytes." (PMID 39285950, 2022). "Diabetes-induced alterations in cardiac PGAM5 expression were explored in mice injected with streptozotocin (STZ)." (PMID 39285950, 2022). "First, PGAM5 protein expression is upregulated and correlates with impaired heart function during STZ-induced diabetes in mice." (PMID 39285950, 2022). "PGAM5 levels in subgroups of hypertension (HTN), diabetes mellitus (DM), and age." (PMID 36389083, 2022). "Both qPCR and western blotting showed that baseline cardiac PHB2 expression was not affected by either diabetes induction or cardiac-specific Pgam5 KO." (PMID 39285950, 2022).
diabetic kidney disease (2 papers, 2022 to 2026). Progressive kidney disorder caused by vascular damage to the glomerular capillaries, in patients with diabetes mellitus. "Empaglifozin improves the diabetic kidney disease by alleviating mitochondrial fission via AMPK/SP1/PGAM5 pathway." (PMID 35456336, 2022).
epilepsy (2 papers, 2022 to 2023). A brain disorder characterized by episodes of abnormally increased neuronal discharge resulting in transient episodes of sensory or motor neurological dysfunction, or psychic dysfunction. "After the knockdown of PGAM5 expression by the adeno-associated virus, an epilepsy model was created by kainic acid." (PMID 36618822, 2022). "Altered PGAM5 expression may be a phenomenon caused by epilepsy that indicates PGAM5 plays a causal role in seizures." (PMID 36618822, 2022). "It is unclear whether PGAM5 is involved in epilepsy and is associated with PINK1-mediated mitophagy." (PMID 36618822, 2022). "Next, we investigated whether PGAM5 is associated with mitophagy in a KA-induced epilepsy model." (PMID 36618822, 2022). "This suggests that PINK1 may be critical for increased mitophagy caused by PGAM5 in epilepsy." (PMID 36618822, 2022). "Western blot, immunohistochemistry and qPCR analysis were used to verify the relationship between PGAM5 and epilepsy by measuring the PGAM5 levels between the KA-induced TLE model and normal control mice." (PMID 36618822, 2022). "Our study suggests that the knockdown of PGAM5 has a significant attenuating effect on epilepsy via mitophagy." (PMID 36618822, 2022). "To investigate the role of PGAM5 on oxidative stress in a KA-induced epilepsy model, we examined the ROS probe dihydroethidium (DHE) to detect ROS accumulation in mouse hippocampal neurons." (PMID 36618822, 2022). "We report that the knockdown of PGAM5 inhibits mitophagy, attenuates seizures, and improves neuronal survival in a KA-induced epilepsy model." (PMID 36618822, 2022). "PINK1 expression is increased in our epilepsy model and decreased PINK1 levels are detected in the epilepsy model after inhibition of PGAM5." (PMID 36618822, 2022). "A recent study reported that PGAM5 was also up-regulated in kainate-induced epilepsy model." (PMID 37221611, 2023). "A higher PGAM5 level was found in epilepsy, and its cellular localization was in neurons." (PMID 36618822, 2022). "Therefore, we investigated the role of PGAM5 in the development and progression of epilepsy as an important molecule role in regulating mitochondrial homeostasis." (PMID 36618822, 2022). "In conclusion, our findings report the unnoticed but important role of PGAM5 in epilepsy." (PMID 36618822, 2022). "The purpose of the present study was to examine whether PGAM5 affects epilepsy through PTEN-induced putative kinase 1 (PINK1)-mediated mitophagy." (PMID 36618822, 2022). "However, reduced mitochondrial swelling and fragmentation are found after the inhibition of PGAM5, which suggests that the knockdown of PGAM5 is crucial for reducing mitophagy in epilepsy." (PMID 36618822, 2022). "Collectively, these data revealed that PGAM5 could reduce PINK1 expression to inhibit mitophagy activity during epilepsy after AAV intervention." (PMID 36618822, 2022). "In addition, the duration of spontaneous seizure-like events (SLEs), the number of SLEs and the time spent in SLEs were all reduced in the epilepsy model after inhibition of PGAM5 expression." (PMID 36618822, 2022). "Therefore, the purpose of this study was to observe the changes of mitophagy in the KA-induced epilepsy model after the inhibition of PGAM5 to clarify the potential mechanism." (PMID 36618822, 2022). "Herein, we address the possible mechanism of PGAM5 in epilepsy based on our study." (PMID 36618822, 2022). "Neuronal cell death is the main pathological outcome after seizures, thus the results suggest that PGAM5 may play an important role in epilepsy." (PMID 36618822, 2022). "Besides, PGAM5 is significantly up-regulated in the late stage of epilepsy." (PMID 36618822, 2022). "During the progression of epilepsy, increased PGAM5 maybe contributes to mitochondrial damage." (PMID 36618822, 2022). "Therefore, PGAM5 is a potential target for epilepsy therapy." (PMID 36618822, 2022). "All these studies reveal that PGAM5 may regulate mitophagy in epilepsy via PINK1." (PMID 36618822, 2022).
epilepsy (continued). "Therefore, PGAM5 knockdown AAV was used to investigate whether PGAM5 level regulated epilepsy activity in the KA-induced TLE mouse model." (PMID 36618822, 2022). "However, the mechanism of PGAM5 in epilepsy remains unclear." (PMID 36618822, 2022). "The interactions between PGAM5 and PINK1 in epilepsy were further found." (PMID 36618822, 2022). "More importantly, the interaction between PGAM5 and PINK1 is found in the epilepsy model." (PMID 36618822, 2022). "Considering that most of the neurons had died in this period, it may be necessary to find surviving neurons in epilepsy models to rule out the effect of dead neurons on PGAM5 expression." (PMID 36618822, 2022).
heart failure (2 papers, 2024). Inability of the heart to pump blood at an adequate rate to meet tissue metabolic requirements. "Furthermore, Pgam5 inhibition was shown to retard heart failure progression via a mechanism involving Keap1/Nrf2‐mediated ferroptosis." (PMID 39143739, 2024).
Hyperglycemia (2 papers, 2022 to 2024). An increased concentration of glucose in the blood. "In summary, the research aligns with the broader theme of mitochondrial dysfunction in cardiac health while providing unique insights into the synergistic roles of Pgam5 and Phb2 in hyperglycemia-induced myocardial dysfunction." (PMID 38818468, 2024). "qPCR analysis revealed that Pgam5 siRNA transfection led to the downregulation of hyperglycemia-induced Drp1, Mff, and Fis1 expression." (PMID 38818468, 2024). "Collectively, our findings indicate that Pgam5 plays a significant role in the hyperglycemia-induced mitochondrial dysfunction pathway, suggesting a novel therapeutic target for mitigating cardiomyocyte damage in hyperglycemic conditions." (PMID 38818468, 2024). "Initially, we observed a significant downregulation in Phb2 transcription upon hyperglycemia exposure, which was countered by Pgam5 deletion, thereby sustaining Phb2 abundance." (PMID 38818468, 2024). "In an effort to elucidate the role of Pgam5 in hyperglycemia-induced cardiomyocyte impairment and mortality, we embarked on a rigorous investigation employing primary cardiomyocytes." (PMID 38818468, 2024). "Employing the MTT assay to gauge cell viability, we discovered that hyperglycemia notably reduced viability, a repercussion that was tempered by Pgam5 siRNA." (PMID 38818468, 2024). "The study's focus on the roles of Pgam5 and Phb2 in hyperglycemia-induced myocardial dysfunction adds to the growing body of research linking mitochondrial dynamics to cardiac health under diabetic conditions." (PMID 38818468, 2024). "Overall, our data suggest a regulatory pathway where Pgam5 modulates mitochondrial fission and mitophagy via Phb2, offering insights into potential therapeutic targets for hyperglycemia-induced cardiomyocyte dysfunction." (PMID 38818468, 2024). "To probe the association between Phb2 and Pgam5-mediated mitochondrial dynamics, we transfected siRNA against Phb2 into Pgam5-silenced cardiomyocytes prior to hyperglycemia treatment." (PMID 38818468, 2024). "The study elucidates the critical roles of Pgam5 and Phb2 in regulating mitochondrial dynamics in the setting of hyperglycemia-induced myocardial dysfunction." (PMID 38818468, 2024). "This manuscript focuses on the role of Pgam5 and Phb2 in hyperglycemia-induced myocardial dysfunction." (PMID 38818468, 2024). "The combined data suggest a protective role for both Pgam5 knockdown and Phb2 overexpression against hyperglycemia-induced cellular and mitochondrial damage." (PMID 38818468, 2024). "Key findings include the observation that Pgam5 knockdown attenuates hyperglycemia-mediated cardiomyocyte death and dysfunction." (PMID 38818468, 2024). "The study also reveals that hyperglycemia-induced mitochondrial dysfunction is influenced by Pgam5, as Pgam5 siRNA transfection mitigates mitochondrial impairment." (PMID 38818468, 2024). "Immunofluorescence showed that, in the presence of hyperglycemia, the interaction between PGAM5 and PHB2 was enhanced relative to the baseline." (PMID 39285950, 2022). "Following exposure to hyperglycemia, the stabilizing effects of Pgam5 deletion on ΔΨm and mtROS production were negated by expression of the HA-PHB2S91A, but not the HA-PHB2S91D, mutant protein." (PMID 39285950, 2022). "In contrast, and suggesting a critical role for PGAM5 in hyperglycemia-mediated suppression of mitochondrial biogenesis, these expression changes were nullified in STZ-treated Pgam5CKO mice." (PMID 39285950, 2022). "Similarly, while Pgam5 deletion maintained the transcription of Parkin, Fundc1, and Bnip3, this effect was abrogated by Phb2 siRNA in hyperglycemia-treated cardiomyocytes." (PMID 38818468, 2024). "Furthermore, qPCR assays revealed that HA-PHB2S91A transfection blunted the positive effect of Pgam5 deletion on mitochondrial biogenesis by reinstating transcriptional downregulation of Pgc1α and Nrf2 in hyperglycemia-exposed cells." (PMID 39285950, 2022).
Hyperglycemia (continued). "Likewise, transfection with HA-PHB2S91A, but not HA-PHB2S91D, reinstated hyperglycemia-mediated mitochondrial complex I/V inactivation in Pgam5-deficient cells." (PMID 39285950, 2022). "Co-immunoprecipitation (Co-IP) assay further verified that the interaction between PGAM5 and PHB2 was induced upon hyperglycemia treatment." (PMID 39285950, 2022). "It elucidates how Pgam5 knockdown ameliorates hyperglycemia-induced cardiac dysfunction 27, contrasting with some studies that have not emphasized Pgam5's role in cardiac health under hyperglycemic stress." (PMID 38818468, 2024). "Herein, we found that hyperglycemia had no influence on PHB2 transcription/expression but reduced the levels of p-PHB2S91 through a mechanism dependent on the phosphatase activity of PGAM5." (PMID 39285950, 2022). "Furthermore, we observed a marked increase in mitochondrial reactive oxygen species (mROS) levels following hyperglycemia treatment, which was notably absent in cells transfected with Pgam5 siRNA." (PMID 38818468, 2024).
liver diseases (2 papers, 2024). "Moreover, PGAM5 has been previously associated with various liver diseases, including acute liver injury, sepsis-induced liver injury, and liver cancer." (PMID 39471139, 2024). "Phosphoglycerate mutase/protein phosphatase (PGAM5)-mediated cell death plays an important role in multiple liver diseases." (PMID 39471139, 2024). "Future research should focus on validating these findings in human studies and exploring the broader implications of Pgam5 and VDAC1 modulation in liver diseases." (PMID 38464835, 2024).
non-small cell lung carcinoma (2 papers, 2018). A group of at least three distinct histological types of lung cancer, including non-small cell squamous cell carcinoma, adenocarcinoma, and large cell carcinoma. "Moreover, studies on the PGAM5/FUNDC1/BCL-xL/DRP1 axis described previously in non-small cell lung cancer points toward the direction that targeting mitophagy through FUNDC1 in combination with X-ray irradiation could improve treatment of this type of human cancer." (PMID 30250843, 2018).
ovarian carcinoma (2 papers, 2019 to 2023). A malignant neoplasm originating from the surface ovarian epithelium. "It was showed that SKOV3 ovarian cancer cells treatment with ALT (64 μM) significantly increased mRNA and protein levels of PGAM5 (Fig.s." (PMID 37712005, 2023).
prostate tumor (2 papers, 2019 to 2025). "Similarly, the mitochondrial protein PGAM5, which regulates oxidative stress responses and the ROS-induced cell death pathway (known as oxeiptosis), exhibits increased expression in high-grade prostate tumors and down-regulated following castration therapy." (PMID 41468516, 2025).
Sepsis (2 papers, 2024 to 2025). Sepsis is defined as life-threatening organ dysfunction caused by a dysregulated host response to infection. "Based on our previous research, we further explored the role of mitophagy dysfunction mediated by VDAC1 and its upstream regulatory protein PGAM5 in sepsis-induced coronary microvascular injury." (PMID 39664568, 2024). "Our findings suggest that PGAM5-mediated mitophagy dysfunction may be a crucial factor leading to sepsis-induced microvascular injury, primarily interacting with VDAC1-mediated mitochondrial membrane dysfunction." (PMID 39664568, 2024).
steatosis (2 papers, 2023). Increased lipid within the cytoplasm of cells. "In HepG2 cells with steatosis, PGAM5 knockdown reduced insulin sensitivity, increased mTOR phosphorylation and reduced the expression of NRF2, catalase (CAT), HO-1 and GPX6." (PMID 37605246, 2023). "Our study demonstrated that PGAM5-KO protected mice from HFHF-diet induced NASH in terms of reduced steatosis, liver injury, inflammation and pro-fibrotic genes." (PMID 37605246, 2023). "Further, PGAM5 knockout ameliorates palmitate-induced steatosis and reduces expression of FABP1 in HepG2 and Huh7 cell lines." (PMID 37835490, 2023). "In conclusion, there were distinct effects of PGAM5 deletion on steatosis, inflammation and fibrosis in NASH models induced by HFHF and MCD (MCS as control) diets." (PMID 37605246, 2023). "In human livers with steatosis, we observed a trend of increase of PGAM5 expression especially around the site of cell ballooning." (PMID 37605246, 2023). "Treatment with the long-chain fatty acid palmitate upregulates PGAM5 mRNA expression and knockout of PGAM5 attenuates palmitate-induced steatosis." (PMID 37835490, 2023). "Palmitate-induced steatosis was significantly reduced in PGAM5 KO compared to WT cell lines." (PMID 37835490, 2023).
Acute hepatitis (1 paper, 2023). Acute hepatic injury resulting from inflammation typically accompanied by increased serum alanine transaminase activity. "The resolving of hepatic injury in conA-induced acute hepatitis model was largely resulting from the regulative effect of PGAM5 on programmed cell death." (PMID 37605246, 2023).
atherosclerosis (1 paper, 2025). A disease characterized by the build-up of fatty material and calcium deposition in the arterial wall resulting in partial or complete occlusion of the arterial lumen. "Mechanistically, leucine deficiency reduced SLC7A5-PGAM5 binding in macrophages, promoting PGAM5-NDUFV1 interaction and enhancing mitochondrial function, which attenuates atherosclerosis progression." (PMID 41270215, 2025).
brain ischemia (1 paper, 2025). Diminished or absent blood supply to the brain caused by obstruction (thrombosis or embolism) of an artery resulting in neurologic damage. "In models of brain ischemia and traumatic brain injury, upregulation of NRF2 expression was used as a surrogate marker of PGAM5 inhibition following treatment with LFHP-1c." (PMID 40361499, 2025).
carcinoma in situ (1 paper, 2018). "PGAM5 was expressed by the malignant epithelial cells of all tumours (n = 29), whether they were adenocarcinomas or squamous cell carcinoma and in pre-neoplastic epithelium (squamous dysplasia and carcinoma in situ)." (PMID 30526542, 2018). "Benign bronchial and alveolar epithelial cells do not express PGAM5 while pre-neoplastic epithelium such as squamous dysplasia and carcinoma in situ express PGAM5." (PMID 30526542, 2018).